TNF (tumor necrosis factor)
Diseases named in the same sentence as TNF in open-access papers (continued):
Sharing a sentence is not in itself a finding about the gene and the disease.
cancer (continued). "Therefore, a more detailed understanding of the additional signaling events that control this switch should provide novel approaches for therapeutic intervention in RIP1 or TNF-driven pathologies such as chronic inflammatory diseases, ischemia-reperfusion injuries and cancer." (PMID 22848449, 2012). "Moreover, given that TNF-α contributes to progression of several cancers, reducing TNF-α levels in AML using MMP inhibitors may dampen the inflammatory milieu in the BM microenvironment; however further studies are required to confirm it." (PMID 24213464, 2012). "Thus, pharmaceutical application of TNFα or TNFα inhibitors in cancer treatment remains debatable." (PMID 22947142, 2012). "There is also evidence, however, that TNF-α may promote the development and spread of the cancer." (PMID 23028877, 2012). "Thus, macrophage-derived cytokines, such as IL-6 and TNF-α, might be promising therapeutic targets for cancer cachexia." (PMID 23326296, 2012). "Of a particular significance are two TNF-α SNPs (SNP -308 G>A and -1031 T>C in the promoter region) and one TNFRSF1B SNP (+676 T>G in exon 6), which have been widely investigated for their associations with susceptibility to and progression and prognosis of various cancers." (PMID 21995493, 2011). "Moreover, that elevated levels of TNF α occur in the blood of patients with malignant tumors." (PMID 20640152, 2010). "Another important molecule affected by TNFα is the gene RYK receptor like tyrosine kinase (RYK) that like RTKs are deregulated in cancers and our revelation of the regulation of its gene expression by TNFα in HepG2 cells could provide information surrounding these phenomena." (PMID 20140224, 2010). "Similarly, anti-TNF therapy may have a spectrum of influence upon de novo malignancy, carcinoma in situ (CIS), and preexisting malignancy." (PMID 20535785, 2010). "In addition, there is in vitro evidence that TNF-α produced by cancer cells may be responsible for stimulation of osteoclast activity and the resulting bone resorption." (PMID 20923560, 2010). "Thus, HDACi such as MS-275 displaying dual TNF-dependent proapoptotic and costimulatory activities might be favored for inclusion in HDACi-based anti-cancer therapeutic strategies." (PMID 19759901, 2009). "Overexpression of CK2 in cancer cells protects cells from etoposide- and diethylstilbestrol-induced apoptosis, results in suppression of apoptosis mediated by tumor necrotic factoralpha (TNF-α), TRAIL and Fas L, and augments apoptosis in cells responsive to these ligands." (PMID 19419583, 2009). "Therapeutic agents are already in development that target acute inflammatory mediators such as TNF-a or IL-1, and their use immediately after surgery might be able to disrupt the subsequent growth factor release essential to residual cancer cell survival and proliferation." (PMID 19383172, 2009). "Hence, TNF-α is present at least in some quantities in most of the carcinoma tissue specimens." (PMID 18257926, 2008). "However, combination treatments that allow the use of lower nontoxic doses and/or prevent cell resistance might still offer opportunities for TNF in the treatment of cancer." (PMID 15138489, 2004). "Moreover, the increase of TNF alpha secretion, instead of inducing cancer cell apoptosis, could produce potential systemic deleterious effects in patients." (PMID 12698185, 2003). "Parthenolide, a strong pan-anti-inflammatory and anti-cancer compound, prevented WSP-induced dysregulation of gap junction activity and TNF mRNA expression." (PMID 41938737, 2026). "TNF-α and endothelial cell interactions promote CRC progression by inducing proinflammatory, procoagulant, and mesenchymal changes in both endothelial and cancer cells, primarily through NF-κB activation and related signaling pathways." (PMID 40558596, 2025).
cancer (continued). "In cancerous cells, dysregulation of oncogenes and the release of pro-inflammatory cytokines such as TNFα increase AP1 activity, which facilitates the proliferation of tumors and the metastasis of cancer cells to other tissues." (PMID 41459064, 2025). "Studies show that KD reduces inflammatory cytokines (TNF-α, IL-1β, IFN-γ), potentially improving cancer treatment and prevention." (PMID 41398969, 2025). "Inflammatory cytokines: The inflammatory microenvironment of tumors (including cytokines such as Interleukin-1 (IL-1) and Tumor Necrosis Factor-alpha (TNF-α) has been shown to stimulate MMP secretion and increase cancer cell invasion." (PMID 41356146, 2025). "We concentrated on the expression level of pro-inflammatory cytokines (IL-1, IL-6, and TNF-a) and HERV genes involved in neuro-inflammatory and cancer processes." (PMID 40143237, 2025). "TNF and other death ligands can—in principle—be provided by many cells within the TME, including autocrine secretion from cancer cells upon stimulation, cytotoxic T cells, but potentially also other cells within the TME." (PMID 40858106, 2025). "The binding of TNF-α to TNFR2 was shown to contribute to the immunosuppressive effects in the TME and promoted cancer cell survival via the NF-κB pathway." (PMID 39883638, 2025). "Considering this mechanism, combination therapy involving TNF-α and NF-κB activation as well as elevated Cyt-C can sensitize Caco-2 cells to boost TNF-α-mediated apoptosis and inflammation to cure cancer." (PMID 40341222, 2025). "CD8+ T cells mediate cancer cell killing through mechanisms involving granzyme and perforin expression and secretion of cytokines such as interferon γ (IFN γ) and TNFα." (PMID 40547943, 2025). "AMK polysaccharide • Enhanced phagocytosis by BMDMs• Activated expression and secretion of immunomodulatory factors (IL-6, IFN-λ, TNF-α, and NO) in BMDMs through TLR4 and MyD88The TLR4/MyD88 pathway plays a vital role in anti-cancer effects of AMK." (PMID 40144663, 2025). "Both studied lncRNAs have been proposed as regulators of cancer-dependent inflammatory responses, targeting the STAT3 and NF-κB pathways and promoting the production of pro-inflammatory cytokines such as TNF-α." (PMID 40150019, 2025). "Inflammatory mediators such as tumor necrosis factor–alpha (TNF-α), interleukin (IL)-6, transforming growth factor–beta (TGF-β), and IL-10 play significant roles in cancer development and progression." (PMID 40224487, 2025). "The upregulated genes in cluster 1 were significantly enriched in several cancer-related pathways, including the IL-17 signaling pathway, the PI3K-Akt signaling pathway, and the TNF signaling pathway." (PMID 40255077, 2025). "Among these, Col4a6 and Csf2 genes participated in inflammation-to-cancer progression by regulating the PI3K-Akt and TNF pathways." (PMID 41415031, 2025). "We found that ECGs were significantly enriched in the TNF‐α/NF‐κB, KRAS and IL‐6/JAK/STAT3 pathways across nearly all cancer types." (PMID 40576208, 2025). "TGF-β, TNF-α, IL-6, and IL-10 are a few pro-inflammatory cytokines that regulate TME in TNBC and promote cancer progression and invasiveness." (PMID 40933989, 2025). "M1 macrophages secrete pro-inflammatory cytokines [IL1, IL6, and tumor necrosis factor (TNF)-α] that activate cytotoxic T lymphocytes (CD8+ T cells) and NK cells to eliminate cancer cells." (PMID 40902549, 2025). "In our study, we confirmed the effects of TNFα, TWEAK, and cancer patient serum on muscle atrophy and the inhibition of muscle differentiation." (PMID 40283883, 2025). "AM52.1CAR T cells produced pro-inflammatory cytokines, including macrophage inflammatory protein 1 beta (MIP-1β), interleukin (IL-8), interferon gamma (IFN-γ), tumor necrosis factor alpha (TNF-α), and IL-13, in response to STn-positive cancer cells." (PMID 40925376, 2025).
cancer (continued). "Cytokines such as IL-1, IL-6, TNF, and others (TGF-β, IL-22, IL-11) interact with cancer cells, promoting signaling pathways (e.g., IKK-NF-κB, JAK-STAT3, MAPK-AP1) that support cancer progression." (PMID 39996799, 2025). "This resulted in the inhibition of the TNF-α induced fusion of M13SV1-Cre human breast epithelial cells and MDA-MB-435-pFDR1 cancer cells." (PMID 40471394, 2025). "Researchers found that tumor necrosis factor α (TNFα) activates the NF-κB pathway in RCC cells, leading to p65 binding at the Rictor promoter and ultimately promoting cancer metastasis." (PMID 39901876, 2025). "In cancer cells, these exosomes have been found enriched with certain biomolecules such as NF-κB, STAT3, and pro-inflammatory cytokines (e.g., TNF-α, IL-1β, and IL-6); this means cancer cell-derived exosomes recruit immune cells to target sites." (PMID 40443670, 2025). "Sustained TNF-α signaling can induce an epithelial-to-mesenchymal transition (EMT) and the expression of matrix metalloproteinases, aiding cancer cell dissemination." (PMID 41007766, 2025). "This review summarizes changes in three major pro-inflammatory cytokines—IL-6, TNF-α, and IL - 1β—in MDD and their influence on cancer progression." (PMID 41000397, 2025). "The convergent surviving cell gene set we identified indicated that pro-survival and anti-apoptotic pathways, such as TNFα via NFkB, PI3K-AKT, and mTOR signaling, are upregulated in polyploid cancer cells." (PMID 39578659, 2025). "Molecular docking further substantiated their therapeutic relevance, showing high binding affinity to key cancer-related targets like AKT1, CDK2, ERK1, and TNFα." (PMID 40942174, 2025). "The reason for this study came from the fact that we already found that minocycline effectively impaired the TNF-α-induced fusion of M13SV1-Cre human breast epithelial cells and MDA-MB-435-pFDR1 human cancer cells." (PMID 40471394, 2025). "ECM degradation also results in the release of sequestered growth factors, such as Tumor Necrosis Factor alpha (TNF-α) and transforming growth factor beta (TGF-β), which further stimulate the proliferation of cancer cells." (PMID 41335396, 2025). "TNF-α is a key pro-inflammatory cytokine in the TME of BCs, produced by stromal cells, particularly M1-polarized TAMs, and by cancer cells themselves." (PMID 40868199, 2025). "The abnormally changed cytokines such as TNF-α and IL-6 in MAE can destroy tissue matrix, promote cancer cell metastasis, and induce the production of VEGF, a key factor crucial for MAE progression." (PMID 41044610, 2025). "The combined action of TNF-α and TGF-β1 can potentiate the activation of signaling pathways and induce robust EMT signatures and cancer cell invasiveness." (PMID 40833805, 2025). "TNF- α directly promotes the reduction of HPV gene transcripts, induces apoptosis in HPV infected/cancer cells and enhances inflammatory response to HPV." (PMID 40259899, 2025). "ALCAR inhibits the synthesis of pro-inflammatory chemokines, TNF-α, and IFN-γ, leading to reduced invasion, proliferation, and migration of cancer cells." (PMID 40430079, 2025). "A small percentage of 1B5 cells, 1.31%, produced TNFα alone or in combination with IFNγ when co-cultured with unpulsed FM3 cancer cells, which increased to 64.7% when co-cultured with peptide-pulsed cancer cells." (PMID 40333248, 2025). "We next measured the secretion of the proinflammatory cytokine TNFα and the anti-inflammatory cytokine IL10 in cocultures of human macrophages and cancer cells (5:1 ratio) incubated with engineered antibodies." (PMID 41128663, 2025). "Our results revealed that TNF EVs significantly enhanced the proliferation, migratory capacity, and EMT of MCF-7 cells and induced a cancer stem cell-like phenotype." (PMID 40567500, 2025). "This action reduces the transcription of pro-inflammatory genes including TNF-α, IL-6, and COX-2, which are commonly upregulated in cancer-related inflammation." (PMID 41226270, 2025).
cancer (continued). "The TFs in M1 and M3 were enriched in transcription al regulation in cancer, MAPK signaling pathway, lipid and AS and TNF signaling pathway." (PMID 40421026, 2025). "Cancer cells secrete mediators such as IL, tumor necrosis factor α (TNF-α), neurotrophic factors, adenosine triphosphate, protons, proteases, and endothelin, which actively stimulate pain-sensing neurons near the cancer." (PMID 40733067, 2025). "Soluble tumor necrosis factor α (solTNFα) binds to TNFR1 to drive inflammation and nerve injury, playing a key role in cancer progression and pain." (PMID 41294802, 2025). "The outer membrane protein Lpp20 activates tumor necrosis factor-alpha (TNF-α) and promotes epithelial-mesenchymal transition (EMT), a process that can trigger metastasis and support cancer progression." (PMID 41392259, 2025). "This potential for TNF-α upregulation is a significant concern in oncology, as TNF-α is a potent activator of the NF-κB pathway, which is well-established to promote cancer cell proliferation." (PMID 41244903, 2025). "Soluble tumor necrosis factor (TNF‐α) related apoptosis inducing ligand (TRAIL), a cancer‐specific drug, shows preclinical efficacy but has a short circulation half‐life." (PMID 39976192, 2025). "Curcumin modulates the expression of several cancer targets, including cyclooxygenase-2 (COX-2), nuclear factor kappa B (NF-κB), STAT-3, tumor necrosis factor-α (TNF-α), and cyclin D1 and is found to decelerate cell growth through cell death and cycle arrest." (PMID 40563255, 2025). "We have demonstrated that minocycline not only suppressed the TNF-α-induced fusion of M13SV1-Cre human breast epithelial cells and MDA-MB-435-pFDR1 cancer cells, but also impaired the proliferation of both cell types in a dose-dependent manner." (PMID 40471394, 2025). "IVIG contains a wide spectrum of proteins participating in cancer response pathways (e.g., anti-DNA, β2glycoprotein-I, Fas, Arg-Gly-Asp (RGD) motif, B cell-activating factor of the tumor necrosis factor (TNF) and more)." (PMID 40630912, 2025). "This process stimulates astrocyte cytokine release (IFN‐α and TNF), activating STAT1 and NF‐κB pathways in cancer cells and promoting BM." (PMID 40719284, 2025). "The predominant pathways included pathways in cancer, the NRF2 signaling pathway, proteoglycans in cancer, the HIF-1 signaling pathway, and the TNF signaling pathway." (PMID 41230084, 2025). "When considering SFV vector therapeutic expectations, SFV/TNFα and SFV/IFNγ serve different functions in cancer treatment." (PMID 40547518, 2025). "Exhausted T cells, arising from chronic antigen exposure within tumors, lose their effector functions, including the ability to kill cancer cells and produce cytokines like IFN-γ and TNF-α." (PMID 40919158, 2025). "To further validate the correlation between elevated TNFR2 levels and increased severity of cachexia, we measured TNFα and TNFR2 concentration in the serum of cancer patients." (PMID 39971710, 2025). "TAMs secrete factors such as TGF-β, EGF, Interleukin (IL)-6, and Tumor Necrosis Factor (TNF)-α, thereby promoting EMT and invasion of cancer cells, supported by in vitro and in vivo studies." (PMID 41465584, 2025). "We have previously constructed an oncolytic adenovirus coding for human TNFα and IL-2, Ad5/3-E2F-d24-hTNFα-IRES-hIL2 (TILT-123 or igrelimogene litadenorepvec) allowing selective replication in cancer cells and high local expression of these transgenes." (PMID 40211048, 2025). "It secretes a plethora of pro-inflammatory cytokines and chemokines, including IL-1β, IL-12, IL-23, IFN-γ, TNF-α, CCL2, and CXCL10, which are pivotal in amplifying the infiltration of anti-tumor immune cells and in the elimination of cancer cells." (PMID 41219968, 2025). "Recent studies have shown that TNF-α stimulates FLS; TNF-α receptor 2 transactivates GRK2 via TRAF2, promoting desensitization of EP4 receptors, which leads to cancer-like proliferation of FLS and contributes to disease progression in RA." (PMID 40224487, 2025).
cancer (continued). "Tumor necrosis factor-alpha (TNF-α), a potent paracrine and endocrine modulator of inflammatory and immunological processes, played a significant role in evaluating the anti-cancer effect of amygdalin in this study through gene expression." (PMID 40097629, 2025). "In most cancers, neutrophil recruitment to the TIME is mediated by several inflammatory cytokines including TNFα, IFNγ, GM-CSF, and IL-8." (PMID 40724900, 2025). "Inflammatory mediators like Interleukin-6 (IL-6) and Tumor Necrosis Factor-alpha (TNF-alpha) activate STAT3 and NF-κB signaling pathways to promote cancer cell proliferation." (PMID 40475789, 2025). "In cancer patients, inflammatory markers like CRP, TNF-α, and interleukins are commonly elevated, reflecting an inflammatory state." (PMID 41387931, 2025). "Immunosuppressive therapies—including thiopurines, calcineurin inhibitors, anti-TNF agents, and JAK inhibitors—are generally withheld until cancer therapy is completed." (PMID 41228267, 2025). "Specifically, nine depsidone compounds were subjected to in silico docking against key cancer-related protein targets, including AKT1, CDK2, ERK1, and TNFα." (PMID 40942174, 2025). "It is rich in tumor necrosis factor α (TNF-α), IL-1β, IL-6, and other chemokines and cytokines, which stimulate cancer cell growth, promote the formation of blood vessels, and reshape the extracellular matrix." (PMID 40244135, 2025). "In this secondary analysis of our randomized controlled CRBP-TS trial, we evaluated the effects of HOET on the cytokines IL-1ß, IL-2, IL-6, IL-10, IL-12p70, TNF-α, IFN-γ, and the mGPS of 145 cancer patients." (PMID 40498221, 2025). "IL6 and TNF are expressed more in the cancer tissue than in the control endometrium which is opposite of what is seen in plasma samples, where both IL6 and TNF are higher in the control subjects." (PMID 40642843, 2025). "Δ Ecto, EphA2-79, and EphA2-85 CAR-T cells, and target cancer cell lines were cocultured to measure interferon (IFN)-γ, tumor necrosis factor (TNF)-α, and Granzyme B, cytokines secreted via killing target cancer cells, using ELISA." (PMID 40181964, 2025). "Analysis of cytokine concentrations revealed significantly elevated levels of pro‐inflammatory cytokines, including TNF‐α, IL‐6, IL‐1β, IL‐8, and VEGF, in cancer tissues compared to adjacent tissues (Fold Change: 2.5–4.0, p < 0.05)." (PMID 40596746, 2025). "Given the complex interactions between TNF-α and HMGCR, elucidating their pathological mechanisms in diseases such as cancer and developing targeted intervention strategies is of significant importance." (PMID 41450917, 2025). "In the CTRL vs LPS groups, the DEGs were mainly enriched in the TNF signaling pathway, MAPK signaling pathway, focal adhesion, and MicroRNAs in cancer." (PMID 40766079, 2025). "For instance, the production of proinflammatory cytokines such as IL-6, IL-1β, and TNF-α is downregulated by the omega-3 PUFA eicosapentaenoic acid (EPA) in healthy people and cancer patients." (PMID 40430444, 2025). "For example, numerous studies show a link between cancer and NFκB or related regulators such as IκB proteins and VEGF and TNFα." (PMID 41459064, 2025). "Cancer cells further secrete cyclic GMP-AMP, which activates the STING pathway, producing the inflammatory cytokines IFN-α and TNF-α in astrocytes." (PMID 39858080, 2025). "TNF-α induces the expression and secretion of CXCL1, CXCL10 and several CCL chemokines in immune cells, endothelial cells and cancer cells." (PMID 40833805, 2025).